MT1IP (metallothionein 1I, pseudogene)
Synonyms: MTE; formerly MT1; MT1I
Gene: Transcribed unprocessed pseudogene on chromosome 16 (56,676,190 to 56,677,742, forward strand). Ensembl gene ENSG00000275691.
Diseases named in the same sentence as MT1IP in open-access papers:
MT1IP is named in the same sentence as 2 diseases in open-access papers, as found by Europe PMC text mining. Sharing a sentence is not in itself a finding about the gene and the disease. The quoted sentences say what the papers report.
liver cancer (1 paper, 2020). An epithelial or non-epithelial malignant neoplasm that arises from the liver. "One of the lncRNAs, MT1IP was reported to act as a tumor suppressor in liver cancer by attenuating cell proliferation and transformation while inducing apoptosis." (PMID 32636408, 2020).
tumour (1 paper, 2020). "Nonetheless, one tumor suppressive network comprising 4 tumour suppressor lncRNAs (MT1DP (seqname: NR_027781 and NR_003658) and MT1IP (seqname: NR_003669 and NR_104046)) and 8 co-expressed genes, enriched in the metallothionein family was identified." (PMID 32636408, 2020). "Though less obvious, the most promising tumor suppressor network comprise 4 lncRNAs (MT1DP isoforms (NR_027781 and NR_003658) and MT1IP isoforms (NR_003669 and NR_104046)) that are co-expressed with 8 genes in the metallothionein family." (PMID 32636408, 2020).